KRTAP19-8 (keratin associated protein 19-8)
Description:
In the hair cortex, hair keratin intermediate filaments are embedded in an interfilamentous matrix, consisting of hair keratin-associated proteins (KRTAP), which are essential for the formation of a rigid and resistant hair shaft through their extensive disulfide bond cross-linking with abundant cysteine residues of hair keratins. The matrix proteins include the high-sulfur and high-glycine-tyrosine keratins.
Tractability: No criterion of Open Targets' tractability assessment is met for any kind of drug.
Gene: Protein-coding gene on chromosome 21 (31,038,159 to 31,038,476, reverse strand). Ensembl gene ENSG00000206102.
Pathways (Reactome):
Developmental Biology: Keratinization
Gene Ontology:
Cellular component: cytosol
Genetic constraint (gnomAD): Missense variants: 19 observed, 24.13 expected, observed/expected ratio (o/e) 0.79, 90% interval 0.55 to 1.15. Synonymous variants: 10 observed, 8.93 expected, observed/expected ratio (o/e) 1.12, 90% interval 0.69 to 1.78.
Homologues: Orthologues: chimpanzee KRTAP19-8 (98% identical).